BRAF (B-Raf proto-oncogene, serine/threonine kinase)
Diseases named in the same sentence as BRAF in open-access papers (continued):
Sharing a sentence is not in itself a finding about the gene and the disease.
ameloblastoma (continued). "In addition, the study of these authors demonstrated the utility of the BRAF p.V600E-specific monoclonal antibody VE1 to detect the BRAF p.V600E mutation in ameloblastomas by immunohistochemistry." (PMID 35048058, 2021). "The study of Diniz and co-workers in 2015 tested whether the BRAF p.V600E mutation was a signature of conventional ameloblastoma or if unicystic lesions also harbored this mutation." (PMID 35048058, 2021). "Moreover, why ameloblastomas show a higher frequency of BRAF mutation than their malignant counterpart, ameloblastic carcinomas, remains a question." (PMID 35048058, 2021). "The following sections addressed the main genetic alterations reported for ameloblastomas, mixed odontogenic tumors, odontogenic carcinomas, where BRAF p.V600E mutation is the most important one, and adenomatoid odontogenic tumors which are characterized by KRAS mutations." (PMID 35048058, 2021). "Notably, ameloblastoma cell lines harboring BRAF p.V600E mutation seem to be sensitive to vemurafenib, i.e., a BRAF small molecule inhibitor, which inhibited cell proliferation and MAPK/ERK activation." (PMID 35048058, 2021). "Key words:Ameloblastoma, whole exome sequencing, somatic mutation, BRAF, HSPA4, two-hit theory." (PMID 33395399, 2021). "Various evidence has highlighted the role of somatic mutations, including recurrent mutation BRAF V600E, in the tumorigenesis of Ameloblastoma, but the intact genetic pathology remains unknown." (PMID 33395399, 2021). "Additionally, single somatic mutations in NRAS and SMO have also been detected in one peripheral ameloblastoma sample each in a mutually exclusive manner with the BRAF mutation." (PMID 35048058, 2021). "It is notable that the presence of two or three gene mutations, including somatic mutations in KRAS, PIK3CA, PTEN, FGFR, CDKN2A, and CTNNB1 in the background of either BRAF or SMO mutation-positive ameloblastomas, exclusively occurred in solid/conventional tumors." (PMID 35048058, 2021). "Following these pieces of research, several studies have also assessed the presence of BRAF p.V600E in conventional ameloblastoma, either by molecular techniques or a combination of mutation screening and immunohistochemistry, with mutation frequencies varying from 55 to ~90%." (PMID 35048058, 2021). "The association between the presence of BRAF p.V600E and ameloblastoma aggressiveness is unclear." (PMID 35048058, 2021). "We previously reported that BRAF mutations were present in more than 85% of ameloblastoma cases." (PMID 32113465, 2020). "As in conventional ameloblastoma, BRAF V600E mutations have been detected." (PMID 32388513, 2020). "Some studies described higher disease-free survival in ameloblastomas with BRAF V600E mutation." (PMID 32388526, 2020). "However, the association between BRAF V600E mutation and clinicopathologic features and behavior of ameloblastoma remains controversial." (PMID 32388526, 2020). "The BRAF Val600Glu mutation was found in the patient with ameloblastoma (case 3)." (PMID 32113465, 2020). "Different authors reported alterations in BRAF mutation frequency for ameloblastoma." (PMID 32388526, 2020). "In 2014, several studies reported the mutation of BRAF V 600E in 40-80% of ameloblastomas." (PMID 32388526, 2020). "Importantly, insulin like growth factor 2 (IGF2), a member of KRAS‐responsive genes, enhances the proliferation of an ameloblastoma cell line AMU‐AM1 with BRAF mutation." (PMID 32096304, 2020). "This malignant tumour shares the BRAF V600E mutation with its benign counterpart, ameloblastoma." (PMID 32388513, 2020). "Since the dependency of clinicopathologic data and BRAF V600E mutation in ameloblastomas remains questionable and conflicting, further studies are required in future to explain the real relationship of this mutation with the aggressiveness of ameloblastoma." (PMID 32388526, 2020). "There is one previous study about the BRAF V600E mutation in Iranian patients with ameloblastoma." (PMID 32388526, 2020).
ameloblastoma (continued). "Several studies have shown that ameloblastomas frequently have a BRAF mutation." (PMID 31340860, 2019). "Several studies have shown that BRAF mutation is frequently present in ameloblastomas." (PMID 31340860, 2019). "However, somatic KRAS, PIK3CA, PTEN, FGFR, CDKN2A, and CTNNB1 co-occurred also in the background of either BRAF- or SMO-mutated ameloblastomas." (PMID 29388014, 2018). "Indeed, two studies have demonstrated in vitro sensitivity of BRAF inhibitors in ameloblastoma cells harboring BRAF V600E mutation, and three other studies have reported successful cases of patients with BRAF V600E mutation treated with BRAF inhibitors." (PMID 30208863, 2018). "Our data suggest that ameloblastomas harboring single BRAF mutations are excellent candidates for neo-adjuvant therapies with combined BRAF/MEK inhibitors and that the risk of recurrence maybe stratified based on the mutational spectrum." (PMID 29388014, 2018). "Thus, we closely examined cases of ameloblastoma with both BRAF and CTNNB1 mutations (cases #19 and #20)." (PMID 28658279, 2017). "Finally, we confirmed by immunohistochemical staining that BRAF Val600Glu was expressed in the 12 ameloblastoma tissues with this mutation." (PMID 28658279, 2017). "Thus, next-generation and direct sequencing collectively indicate that all 14 ameloblastomas harbor either BRAF Val600Glu or NRAS Gln61Arg mutations." (PMID 28658279, 2017). "Recent studies revealed that some ameloblastomas harbour BRAF and SMO mutations that may render them sensitive to new small molecule therapies." (PMID 27965463, 2017). "In particular, BRAF mutations were found in 46–63% of ameloblastoma cases." (PMID 28658279, 2017). "Therefore, alternative treatment options or complementary to surgery have been evaluated, with the most promising one among them being a targeted therapy with the v-Raf murine sarcoma viral oncogene homologue B (BRAF), as in ameloblastoma the activating mutation V600E in BRAF is common." (PMID 38396916, 2024). "This suggests that secondary mutations of BRAF V600E may be exclusive to ameloblastoma." (PMID 38021761, 2023). "Therefore, BRAF V600E mutation was significantly associated with age less than 54 years old among ameloblastoma patients, as shown in the pooled analysis (OR = 3.42; 95% CI = 1.94–6.04; p < 0.0001) based on FEM, as the heterogeneity was not significant (p = 0.11; I2 = 38%)." (PMID 36428683, 2022). "Thus, BRAF p.V600E-mutated ameloblastoma could be pharmacologically vulnerable for precision BRAF-targeting." (PMID 35296678, 2022). "Additionally, we reported EGFR mutations and the presence of other gene mutations, including somatic mutations in KRAS, PIK3CA, PTEN, FGFR, CDKN2A, and CTNNB1 on the background of either BRAF or SMO mutation-positive ameloblastomas, occurring exclusively in conventional AMs." (PMID 36378285, 2022). "In conclusion, we observed that all four Ameloblastoma patients carried BRAF V600E which maybe the first hit crucial for Ameloblastoma susceptibility, and they all carried a second mutation, even a less deleterious one, which may eventually start the tumorigenesis." (PMID 33395399, 2021). "In addition, we established a novel ameloblastoma cell line AMU‐AM1 with BRAF V600E mutation." (PMID 32096304, 2020). "These agents have been tested in patients with BRAF V600E-positive ameloblastoma, with encouraging results." (PMID 41595485, 2026). "Mutations in the MAPK pathway, particularly the activating BRAF V600E mutation, and mutations in the SMO gene of the Sonic Hedgehog signaling pathway, are considered pivotal in the pathogenesis of ameloblastoma." (PMID 41595485, 2026). "CONCLUSIONS: BRAF and RAS mutations were identified in Vietnamese patients with ameloblastoma, with BRAFV600E mutation accounting for more than half of the cases." (PMID 41975369, 2026).
ameloblastoma (continued). "Current research on the pharmacological treatment of ameloblastoma primarily focuses on treating mostly BRAF V600E-positive tumors with MAPK pathway inhibitors." (PMID 41595485, 2026). "BRAF inhibitors such as vemurafenib, dabrafenib, and sorafenib have significantly reduced the size in some metastatic and unresectable ameloblastoma cases." (PMID 41185044, 2025). "Studies have reported that a significant proportion of maxillary ameloblastomas harbor SMO mutations, whereas mandibular tumors are more likely to harbor BRAF mutations." (PMID 40699660, 2025). "Current clinical applications of targeted therapy for ameloblastoma primarily focus on BRAF V600E, with most evidence derived from case reports and small case series." (PMID 41030734, 2025). "This study highlights a high frequency of BRAF V600E immunoreactivity in ameloblastomas among Latin American cases." (PMID 38615253, 2024). "In this series of Latin American ameloblastomas, the positivity for BRAF V600E in unicystic types was statistically higher when compared to conventional types." (PMID 38615253, 2024). "A statistically significant difference in BRAF V600E positivity was observed when comparing unicystic ameloblastomas to conventional ameloblastomas (p=0.03)." (PMID 38615253, 2024). "A total of 86 samples of ameloblastomas were examined for immunohistochemistry using anti-BRAF V600E antibody." (PMID 38615253, 2024). "This study aimed to investigate the frequency of BRAF V600E immunoexpresion in ameloblastomas diagnosed in four Latin American centers and correlate this finding with the histological types and subtypes of the analyzed cases." (PMID 38615253, 2024). "In light of these potential distinctions among the histological subtypes of unicystic ameloblastomas, we combined the results of the luminal and intraluminal types to compare the immunohistochemical expression of BRAF V600E with the mural types." (PMID 38615253, 2024). "Five studies differentiated the immunohistochemical expressions of BRAF V600E between conventional and unicystic ameloblastomas, of which three (60%) demonstrated that the unicystic types exhibited higher positivity compared to the conventional ones." (PMID 38615253, 2024). "Albeit preliminary, these are the first comprehensive histomorphologic findings on BRAF-treated ameloblastomas." (PMID 39621130, 2024). "Treatment with BRAF inhibitors can be effective in reducing ameloblastoma size and facilitate excision." (PMID 38638641, 2024). "BRAF V600E was positive in 38/56 cases (67.9%) of conventional ameloblastomas and in 27/30 cases (90.0%) of unicystic ameloblastomas." (PMID 38615253, 2024). "The present study reveals a high frequency of ameloblastomas displaying positive immunoreactivity for BRAF V600E in a significant sample of Latin American cases." (PMID 38615253, 2024). "This will assist patients, especially in the subtype metastatic ameloblastoma, as BRAF inhibitors have been proven to provide good outcomes." (PMID 39398651, 2024). "The positivity for BRAF V600E in this sample of ameloblastomas was predominantly observed in the odontogenic epithelial cells." (PMID 38615253, 2024). "BRAF-targeted therapy was used effectively for the first time in a neoadjuvant protocol in a small series of young patients with unicystic, mural type ameloblastoma." (PMID 39621130, 2024). "Clinical trials are currently underway to evaluate the effectiveness of BRAF inhibitors and other targeted agents in the management of ameloblastoma, aiming to further refine treatment strategies and optimize patient outcomes." (PMID 38021761, 2023). "Multiple studies have demonstrated that the BRAF-V600E gene mutation contributes to the activation of the MAPK signaling pathway and plays a crucial role in the pathogenesis of ameloblastoma." (PMID 37646022, 2023).
ameloblastoma (continued). "The authors encourage the development of clinical trials in the use of BRAF Inhibitor drugs for select ameloblastoma patients in a high-volume multi-center setting." (PMID 37115331, 2023). "BRAF inhibitors like vemurafenib, dabrafenib, and sorafenib have shown excellent results, especially in metastatic ameloblastoma." (PMID 38021761, 2023). "Vemurafenib, a BRAF inhibitor, has been evaluated in the ameloblastoma-1 cell line and demonstrated a reduction in cell proliferation and activation of the MAPK signaling pathway." (PMID 38021761, 2023). "The detection of BRAF V600E in ameloblastoma is commonly performed using immunohistochemical techniques with specific antibodies." (PMID 38021761, 2023). "BRAF, particularly in the case of metastatic ameloblastoma, inhibitors such as vemurafenib, dabrafenib, and sorafenib, has demonstrated outstanding results." (PMID 38021761, 2023). "We encourage further clinical trials in the use of BRAF Inhibitors for selecting ameloblastoma patients in a multi-center setting." (PMID 37115331, 2023). "The identification of BRAF(V600E) mutation and the amplification of SOX2-positive cells in ameloblastomas imply the possible benefit of applying BRAF and SOX2 inhibitors in recurrent and un-resectable ameloblastomas." (PMID 35055392, 2022). "The meta-analysis result has significantly upheld the correlation of the BRAF gene to ameloblastoma occurrence." (PMID 36428683, 2022). "Hence, there is a possibility that BRAF V600E mutation may play a role in the malignant transformation of ameloblastoma, as this rare odontogenic malignancy has close features that combine the histologic features of ameloblastoma with cytologic atypia." (PMID 36428683, 2022). "Advanced next-generation sequencing (NGS) analyses identified the high frequency of BRAF V600E and SMO L412F mutations in all types of ameloblastoma." (PMID 36378285, 2022). "The first of these is the detection of a high incidence of BRAF V600E and SMO L412F mutations in ameloblastoma." (PMID 36127985, 2022). "It needs further investigation to uncover what roles SOX2 and BRAF play in the tumor biology of ameloblastoma." (PMID 35055392, 2022). "Other than the BRAF gene in the MAPK pathway, FGFR2 and RAS mutations were also part of the pathogenesis of most ameloblastoma cases." (PMID 36428683, 2022). "The BRAF V600E mutation essentially activates MEK/ERK signalling, leading to tumour formation and, in this case, ameloblastoma formation." (PMID 36428683, 2022). "Mutually exclusive and less common mutations affecting other MAPK-related genes, such as KRAS, NRAS, HRAS, and FGFR2 (a receptor whose stimulation activates MAPK/ERK pathway) have been reported in BRAF wild-type ameloblastomas." (PMID 35048058, 2021). "It is notable that the KRAS p.G12R mutation, which occurs in adenomatoid odontogenic tumors, has been reported in 4/50 (8%) and 4/28 (14%) of BRAF wild-type ameloblastoma cases." (PMID 35048058, 2021). "Initially, such mutations have been uncovered in benign epithelial odontogenic tumors wherein BRAF and KRAS mutations were revealed in ameloblastomas and adenomatoid odontogenic tumors, respectively." (PMID 35048058, 2021). "Since BRAF and RAS are in the same MAPK pathway, it is interesting that ameloblastomas, frequently associated with BRAFV600E mutation have aggressive clinical behavior, but in contrast, AOTs, frequently associated with RAS mutations have indolent behavior." (PMID 35048068, 2021). "Mutations in FGFR2 have been described in 4/28 (14%), 3/50 (6%), and 2/39 (5%) of BRAF wild-type conventional ameloblastomas." (PMID 35048058, 2021). "The mutational landscape of odontogenic tumors has not been fully characterized, while some proteins involved in the mitogen-activated protein kinase (MAPK) pathway, such as BRAF, play a pivotal role in the development and progress of ameloblastoma." (PMID 33680332, 2021).
ameloblastoma (continued). "In line with that, in vitro studies and case reports have focused on BRAF-targeted therapy in ameloblastomas." (PMID 35048058, 2021). "BRAF inhibitors offer promising results in the treatment of BRAF-positive ameloblastomas and should continue to be researched in AC and EAC patients." (PMID 32643344, 2020). "In aggressive relapsing and/or metastatic ameloblastoma cases, apart from surgery, anti-BRAF biotherapy can be used." (PMID 32388513, 2020). "It seems that BRAF inhibitors can have clinical benefits and responses in recurrent and metastatic ameloblastomas and use as neoadjuvant and/or targeted adjuvant therapy to improve the treatment outcome, especially in locally advanced ameloblastomas." (PMID 32388526, 2020). "Advanced next generation sequencing (NGS) analyses identified high frequency of BRAF V600E and SMO L412F mutations in ameloblastoma." (PMID 32096304, 2020). "Nearly 90% of ameloblastomas present mutations in genes related to the MAPK pathway, specifically the BRAF V600E, which has diagnostic and prognostic implications." (PMID 31232391, 2019). "Our data confirm previous studies who found that BRAF and SMO are by far the most frequent oncogenic driver mutations in ameloblastomas." (PMID 29388014, 2018). "Remarkably, the unilocular to multilocular pattern rate was higher (1.3:1, 1.5:1, respectively) in the tumors with BRAF and multiple gene mutations, in contrast to SMO, NRAS, HRAS, and EGFR-mutated ameloblastomas (1:3, 1:2, respectively)." (PMID 29388014, 2018). "Nevertheless, some cases of odontogenic tumors genetically overlap, such as ameloblastoma cases #19 and #20, in which BRAF and CTNNB1 are present." (PMID 28658279, 2017). "In contrast, BRAF or NRAS mutations were observed in 12 and two control samples of ameloblastoma, respectively." (PMID 28658279, 2017). "Disruption of the Mitogen-Activated Protein Kinase (MAPK) and Sonic Hedgehog (SHH) signaling pathways, most notably through activating mutations in the BRAF and SMO genes, which are discussed later, appears to play a central role in the pathogenesis and biological behavior of ameloblastoma." (PMID 41595485, 2026). "Our results confirm the absence of BRAF p.V600E mutations in adenomatoid odontogenic tumors (AOTs), in agreement with their recognized distinction from ameloblastomas in current WHO classifications." (PMID 41364259, 2025). "Notably, BRAF V600E mutations are frequently identified in these tumors, and FGFR mutations have also been reported in ameloblastomas." (PMID 39907837, 2025). "Another important distinguishing feature in the current literature is that AdAM typically lacks mutations in the BRAF and p.V600E genes unlike conventional ameloblastoma." (PMID 41306250, 2025). "Additional studies showed gene expression profile differences between plexiform and follicular ameloblastomas, with follicular ameloblastomas expressing variants of BRAF, KMT2D, and ABL1, while plexiform ameloblastomas expressed variants of ALK, BRAF, KRAS, KMT2D, SMO, KMT2A, and BRCA2." (PMID 38607614, 2025). "Regarding conventional ameloblastomas (n=56), 38 cases (67.9%) were positive for BRAF V600E." (PMID 38615253, 2024). "In conventional ameloblastomas, no statistical association was observed between any of their histological variants and BRAF V600E positivity." (PMID 38615253, 2024). "In this context, according to the largest case series reviewed in this study that compared the immunoexpression of BRAF V600E in conventional and unicystic ameloblastomas, there was also a trend indicating that unicystic types exhibit higher positivity for BRAF V600E than conventional types." (PMID 38615253, 2024). "Within the unicystic ameloblastomas, all luminal and mural variants tested positive, while 60% of intraluminal variants were negative for BRAF V600E immunoexpression." (PMID 38615253, 2024).